RNU6-416P (RNA, U6 small nuclear 416, pseudogene)
Gene: Small nuclear RNA gene on chromosome 16 (30,675,300 to 30,675,402, reverse strand). Ensembl gene ENSG00000252074.
Homologues: Orthologues: chimpanzee U6 (100% identical), macaque U6 (86% identical), pig U6 (58% identical). Paralogues in human: RNU6-1060P (81% identical), RNU6-1122P (81% identical), RNU6-1158P (81% identical), RNU6-1187P (81% identical), RNU6-166P (81% identical), RNU6-48P (81% identical), RNU6-574P (81% identical), RNU6-116P (80% identical), RNU6-140P (80% identical), RNU6-15P (80% identical), RNU6-17P (80% identical), RNU6-18P (80% identical), and 1288 more.